RNU6-1024P (RNA, U6 small nuclear 1024, pseudogene)
Gene: Small nuclear RNA gene on chromosome 3 (15,433,110 to 15,433,216, reverse strand). Ensembl gene ENSG00000206926.
Homologues: Orthologues: chimpanzee U6 (97% identical), rabbit U6 (78% identical), rat LOC120098752 (77% identical), mouse Gm56054 (73% identical). Paralogues in human: RNU6-1060P (93% identical), RNU6-15P (93% identical), RNU6-19P (93% identical), RNU6-71P (93% identical), RNU6-949P (93% identical), RNU6-12P (92% identical), RNU6-13P (92% identical), RNU6-166P (92% identical), RNU6-26P (92% identical), RNU6-31P (92% identical), RNU6-32P (92% identical), RNU6-41P (92% identical), and 1292 more.